BRMS1L (BRMS1 like transcriptional repressor)
Description:
Involved in the histone deacetylase (HDAC1)-dependent transcriptional repression activity.
Synonyms: MGC11296; FLJ39177; p40; BRMS1
Tractability: PROTAC: UniProt records ubiquitination sites on it; ubiquitination databases record sites on it; its protein half-life has been measured.
Gene: Protein-coding gene on chromosome 14 (35,826,310 to 35,932,325, forward strand). Ensembl gene ENSG00000100916.
Subcellular location: Nucleus
Subcellular location (Human Protein Atlas): Nucleoplasm
Gene Ontology:
Molecular function: protein binding; histone deacetylase binding
Biological process: negative regulation of cell migration; negative regulation of stem cell population maintenance; negative regulation of transcription by RNA polymerase II; negative regulation of transforming growth factor beta receptor signaling pathway; positive regulation of stem cell population maintenance
Cellular component: nucleoplasm; nucleus; Sin3-type complex
Genetic constraint (gnomAD): Loss-of-function variants: 13 observed, 25.59 expected, observed/expected ratio (o/e) 0.51, 90% interval 0.33 to 0.81. The upper end of that interval is the gene's LOEUF score, 0.81, which puts it in group 3 of 6, group 1 being the genes least tolerant of losing a copy. Missense variants: 184 observed, 218.82 expected, observed/expected ratio (o/e) 0.84, 90% interval 0.75 to 0.95. Synonymous variants: 70 observed, 76.82 expected, observed/expected ratio (o/e) 0.91, 90% interval 0.75 to 1.11.
Homologues: Orthologues: chimpanzee BRMS1L (100% identical), dog BRMS1L (100% identical), macaque BRMS1L (100% identical), pig BRMS1L (100% identical), rat Brms1l (100% identical), mouse Brms1l (99% identical), rabbit BRMS1L (99% identical), guinea pig BRMS1L (99% identical), tropical clawed frog brms1l (90% identical), zebrafish brms1 (43% identical), Drosophila melanogaster Brms1 (31% identical). Paralogues in human: BRMS1 (42% identical), SUDS3 (28% identical).
Diseases named in the same sentence as BRMS1L in open-access papers:
BRMS1L is named in the same sentence as 14 diseases in open-access papers, as found by Europe PMC text mining. Sharing a sentence is not in itself a finding about the gene and the disease. The quoted sentences say what the papers report.
breast carcinoma (9 papers, 2013 to 2026). "In Axis 3, miR-20a-5p↑ SAR1B↓ BRMS1L↓, reduced BRMS1L in breast cancer tissues was shown to be associated with metastasis and poor patient survival." (PMID 34805186, 2021). "However, there are still limited research on breast cancer about BRMS1L, which implicated that in-depth mechanism on carcinogenesis should be explored." (PMID 41282485, 2025). "Furthermore, we analyzed the association between BRMS1L expression and the clinicopathological status of 138 patients with breast cancer." (PMID 41282485, 2025). "Furthermore, BRMS1L expression in breast cancer cells is associated with less metastasis and better clinical outcome." (PMID 41282485, 2025). "SNPs near BRMS1L, a breast cancer suppressor gene, was associated with LMEDn and LDLppd." (PMID 23628382, 2013). "However, it remains obscure whether BRMS1L is associated with autophagy via regulating chemosensitivity of breast cancer cells." (PMID 41282485, 2025). "Our findings reveal a novel role of BRMS1L in chemosensitivity and highlight its potential clinical application in the treatment of breast cancer." (PMID 41282485, 2025). "In vivo experiments further validated that BRMS1L exerts potent antitumor effects, highlighting its potential clinical application in the treatment of breast cancer." (PMID 41282485, 2025). "Our previous study demonstrated that BRMS1L suppresses invasion and metastasis of breast cancer cells by inhibiting EMT." (PMID 41282485, 2025). "In vitro experiments confirmed that chemoresistant breast cancer cells exhibited decreased BRMS1L expression compared to chemosensitive cells." (PMID 41282485, 2025). "In the present study, we were interested in the role of BRMS1L in regulating chemotherapy sensitivity in breast cancer cells." (PMID 41282485, 2025). "The regulation of BRMS1L by chemotherapy in breast cancer cells remains undisclosed; we therefore carried out experiments and demonstrated that chemotherapy-resistant breast cancer cells exhibited decreased BRMS1L expression." (PMID 41282485, 2025). "In summary, our discovery will not only increase our knowledge on the role of BRMS1L in breast cancer but also provide a novel biomarker for developing the sensitizing strategy and predicting response to breast cancer chemotherapy." (PMID 41282485, 2025). "Collectively, these data suggest that BRMS1L enhances chemotherapy sensitivity of breast cancer cells." (PMID 41282485, 2025). "A previous study revealed that BRMS1L suppresses breast cancer invasiveness and metastasis by inhibiting epithelial–mesenchymal transition (EMT)." (PMID 41282485, 2025). "In the present study, we found that reduced BRMS1L expression correlates with poor response to neoadjuvant chemotherapy and unfavorable prognosis in breast cancer patients." (PMID 41282485, 2025). "In this study, we demonstrated that BRMS1L enhanced the chemotherapy sensitivity and subsequently promoted the prognosis of breast cancer patients by inhibiting autophagy." (PMID 41282485, 2025). "RNA interference-mediated silencing of BRMS1L expression promotes metastasis of breast cancer xenografts." (PMID 29760585, 2018). "FZD10 overexpression in breast cancer cells due to reduced breast cancer metastasis suppressor 1 like (BRMS1L) level led to aberrant activation of canonical WNT signaling and thus induced EMT and promoted metastasis." (PMID 29789460, 2018). "BRMS1L plays an important role in cancer cell metastasis regulation such as breast cancer, melanoma, non-small cell lung and ovarian cancer." (PMID 29760585, 2018). "The autocrine hGH-mediated EMT in breast cancer has been shown to be dependent on the hGH-stimulated increase in the expression of microRNA 96-182-183 cluster, which in turn suppressed breast cancer metastasis suppressor 1-like (BRMS1L) expression." (PMID 29262609, 2017).
breast carcinoma (continued). "Functional studies demonstrated that inhibition of miR-4775 significantly attenuated cellular viability, migration, and invasion capabilities, while knockdown of breast cancer metastasis suppressor 1-like‌ (BRMS1L) effectively rescued these suppressive effects." (PMID 41486199, 2026). "In this section, we investigate whether BRMS1L-mediated ATG5 downregulation contributes to the inhibition of autophagy in breast cancer cells." (PMID 41282485, 2025). "Furthermore, chemoresistant breast cancer cells exhibited elevated autophagy levels, and ectopic expression of BRMS1L significantly suppressed protective autophagy through downregulating ATG5." (PMID 41282485, 2025). "BRMS1L has been identified as a breast cancer metastasis suppressor, but its clinical relevance with NACT remains unclear." (PMID 41282485, 2025). "Furthermore, BRMS1L significantly enhanced chemotherapy sensitivity by inhibiting protective autophagy in breast cancer cells." (PMID 41282485, 2025). "Association between BRMS1L expression and clinicopathologic features of 138 breast cancer patients [No (%)]." (PMID 41282485, 2025). "Thus, we demonstrated that BRMS1L significantly enhanced chemotherapy sensitivity via inhibiting protective autophagy in breast cancer cells." (PMID 41282485, 2025). "The results suggested that autophagy would occur on MCF-7 and MCF-7/ADR cells; however, it remains unclear whether autophagy also occurs under the influence of BRMS1L on breast cancer cells." (PMID 41282485, 2025). "However, overexpression of BRMS1L significantly inhibited the growth of breast cancer xenograft tumors upon ADM treatment." (PMID 41282485, 2025). "Thus, BRMS1L provides an epigenetic regulation of Wnt signalling and suppresses a breast cancer metastasis." (PMID 29760585, 2018). "Additionally, chemoresistant breast cancer cells exhibited decreased BRMS1L expression." (PMID 41282485, 2025). "Breast cancer metastasis suppressor 1 like (BRMS1L), a core component of the Sin3A–histone deacetylase (HDAC) co-repressor complex, has been reported to suppress breast cancer metastasis through epigenetically regulating the Wnt signal pathway." (PMID 41282485, 2025). "Collectively, these results indicated that BRMS1L suppresses ATG5 expression, which inhibits the ADM-induced protective autophagy in breast cancer cells." (PMID 41282485, 2025). "BRMS1L-induced FZD10 epigenetic silencing through HDAC1 recruitment and histone H3K9 deacetylation at the promoter can suppress breast cancer metastasis by inhibiting aberrant activation of WNT3-FZD10-β-catenin signaling." (PMID 30286088, 2018).
non-small cell lung carcinoma (3 papers, 2015 to 2025). A group of at least three distinct histological types of lung cancer, including non-small cell squamous cell carcinoma, adenocarcinoma, and large cell carcinoma. "BRMS1L (breast cancer metastasis suppressor 1-like) is a transcription factor with tumor-suppressive functions reported in breast, ovarian, and non-small cell lung cancer, where it inhibits migration and invasion, thereby limiting metastasis." (PMID 40943553, 2025).
ovarian carcinoma (3 papers, 2018 to 2025). A malignant neoplasm originating from the surface ovarian epithelium. "For example, BRMS1L suppresses metastasis by inhibiting the β-catenin/wnt pathway in ovarian cancer." (PMID 41282485, 2025). "Our findings report for the first time that miR-93 promotes LACC cell EMT, migration, and invasion via targeting downregulation of BRMS1L through regulation of Wnt signaling pathway, which differs from its anti-oncogene role in ovarian cancer." (PMID 29760585, 2018). "Thus, as previously noted, in case #25, OGM detailed the inversion of the long arm of chromosome 14 and showed that the breakpoints are located next to the BRMS1L gene at 14q32.13, a gene involved in breast and ovarian cancer, and next to the TCL1A locus at 14q13.2." (PMID 37046792, 2023).
glioma (1 paper, 2021). A benign or malignant brain and spinal cord tumor that arises from glial cells (astrocytes, oligodendrocytes, ependymal cells). "HDAC-related genes upregulated in IDH1/2mut glioma include HDAC2/4/5, KDM1A, CHD4, MTA2/3, SIRT1/2, PHF21A, and BRMS1L." (PMID 34424450, 2021).
kidney cancer (1 paper, 2025). Primary or metastatic malignant neoplasm involving the kidney. "Based on its function in other malignancies, we hypothesized that BRMS1L may have similar relevance in RCC and serve as a biomarker, and its restoration could offer therapeutic benefits in kidney cancer." (PMID 40943553, 2025).
pancreatic carcinoma (1 paper, 2026). "METHODS: Quantitative Real-Time Reverse Transcription (RT-qPCR) was performed to analyze miR-4775 and BRMS1L expression levels in both human PC tissues and human pancreatic carcinoma cells‌ (PANC-1) lines." (PMID 41486199, 2026).
viral infection (1 paper, 2021). "While BRMS1L has been described as a metastatic suppressor gene, TRIM25 has been involved in numerous cellular processes including regulation of innate immune response against viral infection." (PMID 34899750, 2021).
cancer (8 papers, 2008 to 2026). A tumor composed of atypical neoplastic, often pleomorphic cells that invade other tissues. "CONCLUSIONS: These findings demonstrate that miR-4775 regulates PC progression by modulating cancer cell viability, migration, and invasion through BRMS1L-mediated mechanisms." (PMID 41486199, 2026). "Additionally, these cluster members facilitate cancer invasion, EMT, and metastasis through commonly targeting breast cancer metastasis-suppressor 1-like (BRMS1L)." (PMID 33066509, 2020). "BRMS1L plays an important role in cancer cell metastasis regulation." (PMID 29760585, 2018). "Furthermore, we identified cancer-related genes aberrantly expressed in ccRCC (BRMS1L, CPEB3, DNAJB9, KIF3B, NFIB, PTPRJ, RBL2) and targeted by members of the miR-106b-25 cluster, suggesting that their dysregulation may be driven by these miRNAs." (PMID 40943553, 2025). "ATAD2, BRMS1L, PUF60, SHQ1, and USP4 were found to influence overall survival in 15, 9, 13, 13, and 12 of the 21 cancer types, respectively." (PMID 39127727, 2024). "Survival analysis showed that several of the dysregulated genes (e.g. ATAD2, BRMS1L, PUF60, SHQ1, and USP4) have an impact on prognosis in multiple cancer types, thereby further highlighting the clinical significance of aberrant gene expression patterns on patient survival." (PMID 39127727, 2024).
tumor (3 papers, 2014 to 2025). "It revealed that high BRMS1L expression was associated with a smaller tumor size, lower grade, less lymph node involvement, and lower relapse rate." (PMID 41282485, 2025). "Previous studies revealed the tumor suppressor role of BRMS1L in several types of malignancies." (PMID 41282485, 2025). "BRMS1L, CPEB3, KIF3B, NEDD4L, PTPRJ, and RBL2 were significantly downregulated in tumor samples compared to controls." (PMID 40943553, 2025).
infection (1 paper, 2025). The state of being infected such as from the introduction of a foreign agent such as serum, vaccine, antigenic substance or organism. "To explore the relationship between autophagy and chemotherapy sensitivity, we transfected the cells with GFP–LC3 plasmid to visualize the autophagy after silencing or enforcing BRMS1L, and we found that following ectopic BRMS1L infection, GFP–LC3 was reduced in MCF/ADR cells." (PMID 41282485, 2025).
BRMS1L also shares sentences with these, for which no sentence is quoted: brain cancer (1 paper); esophageal squamous cell carcinoma (1); lacrimal gland adenoid cystic carcinoma (1); melanoma (1).